PID1 (phosphotyrosine interaction domain containing 1)
Description:
Increases proliferation of preadipocytes without affecting adipocytic differentiation.
Synonyms: P-CLI1; NYGGF4; PCLI1; HMFN2073; FLJ20701
Tractability: PROTAC: its protein half-life has been measured.
Gene: Protein-coding gene on chromosome 2 (228,850,526 to 229,271,867, reverse strand). Ensembl gene ENSG00000153823.
Subcellular location: Cytoplasm
Subcellular location (Human Protein Atlas): Endoplasmic reticulum
Gene Ontology:
Molecular function: protein binding
Biological process: fat cell differentiation; mitochondrion organization; negative regulation of ATP biosynthetic process; negative regulation of D-glucose import; negative regulation of insulin receptor signaling pathway; negative regulation of protein localization to plasma membrane; positive regulation of fat cell proliferation; positive regulation of gene expression; positive regulation of reactive oxygen species metabolic process; positive regulation of transcription by RNA polymerase II; cellular response to cytokine stimulus; cellular response to fatty acid; cellular response to interleukin-6; cellular response to tumor necrosis factor; energy reserve metabolic process; positive regulation of ATP biosynthetic process; regulation of mitochondrial fusion; regulation of mitochondrial membrane potential; regulation of reactive oxygen species metabolic process; cellular response to leptin stimulus; regulation of ATP biosynthetic process; regulation of cell population proliferation
Cellular component: cytoplasm
Genetic constraint (gnomAD): Loss-of-function variants: 9 observed, 17.36 expected, observed/expected ratio (o/e) 0.52, 90% interval 0.31 to 0.9. The upper end of that interval is the gene's LOEUF score, 0.9, which puts it in group 3 of 6, group 1 being the genes least tolerant of losing a copy. Missense variants: 247 observed, 293.89 expected, observed/expected ratio (o/e) 0.84, 90% interval 0.76 to 0.93. Synonymous variants: 129 observed, 120.21 expected, observed/expected ratio (o/e) 1.07, 90% interval 0.93 to 1.24.
Homologues: Orthologues: macaque PID1 (100% identical), pig PID1 (98% identical), guinea pig PID1 (97% identical), mouse Pid1 (96% identical), chimpanzee PID1 (95% identical), dog PID1 (94% identical), tropical clawed frog pid1 (86% identical), rat Pid1 (77% identical), zebrafish pid1 (67% identical).